RNU6-810P (RNA, U6 small nuclear 810, pseudogene)
Gene: Small nuclear RNA gene on chromosome 22 (29,134,014 to 29,134,120, forward strand). Ensembl gene ENSG00000200871.
Homologues: Orthologues: chimpanzee U6 (98% identical), macaque U6 (93% identical), rat U6 (83% identical). Paralogues in human: RNU6-1011P (89% identical), RNU6-242P (89% identical), RNU6-379P (89% identical), RNU6-38P (89% identical), RNU6-41P (89% identical), RNU6-44P (89% identical), RNU6-11P (88% identical), RNU6-1331P (88% identical), RNU6-28P (88% identical), RNU6-37P (88% identical), RNU6-1117P (87% identical), RNU6-1145P (87% identical), and 1289 more.